CNOT2 (CCR4-NOT transcription complex subunit 2)
Diseases named in the same sentence as CNOT2 in open-access papers (continued):
Sharing a sentence is not in itself a finding about the gene and the disease.
lung adenocarcinoma (1 paper, 2021). A carcinoma that arises from the lung and is characterized by the presence of malignant glandular epithelial cells.
metastatic disease (1 paper, 2016). "The integrated genetics and gene expression analysis that initially identified Cnot2 also implicated other genes associated with RNA deadenylation (Cnot8, Angel2, Tob1) as potential modulators of metastatic disease, suggesting that this function of CCR4-NOT might be a critical determinant." (PMID 26807845, 2016).
oral cancer (1 paper, 2019). "In conclusion, next-generation sequencing analysis revealed that a total of 13 genes (RRP43, RRP42, CSL4, TRF4, Mtr4, RRP6, MPP6, CNOT2, CNOT3, SKI2, Ski3, EDC4, and XRN1) involved in the mRNA degradation pathway were upregulated by PPARα activation in oral cancer cells." (PMID 31724941, 2019).
pulmonary stenosis (1 paper, 2025). "CHD (for example, ventricular septal defects, pulmonary stenosis and dysplastic valves) is known to occur in patients with CNOT2-related disorder and so this finding was consistent with his cardiac presentation." (PMID 39587356, 2025).
thymoma (1 paper, 2020). A neoplasm arising from the epithelial cells of the thymus. "Based on the same PRM validation sample batch we also examined TSCC/thymoma marker candidates such as CNOT2/9, SHMT1, VCAN, HTRA1, and TIMP1 in parallel with CK19 in the PRM analysis (for raw fragment abundances of all PRM samples)." (PMID 31967407, 2020). "To visualize their spatial localizations, we applied immunofluorescent stainings by confocal microscopy in type B thymoma tissues using fluorescent‐labeled antibodies of CNOT2, SHMT1, CK19 (to index thymomas epithelia), and DAPI (nuclei staining)." (PMID 31967407, 2020). "Studies on mRNA‐seq data of thymoma confirm such notion by showing the correlation between the low levels of CNOT2/CNOT9 and the poor survival." (PMID 31967407, 2020). "It was inspiring to find that the expression of CNOT family (CNOT2 and CNOT9) and SHMT1 was highly correlated with the prognosis of thymoma: Patients with lower expression of these genes at transcription level had poor relapse‐free survival (RFS) probability." (PMID 31967407, 2020). "CNOT2, CNOT9, CD99, PRSS16, PSMB11, and SHMT1 were found with high abundance in thymoma and participated mainly in nucleic acid and amino acid metabolism." (PMID 31967407, 2020). "Compared with conventional subtyping markers (e.g., TdT, PRSS16, and PSMB11), CNOT2/9 and SHMT1 not only exhibited good segregating capabilities for thymoma and TSCC, but also showed great prognosis indicating potentials." (PMID 31967407, 2020). "Further comparison of type B3 and TSCC proteome revealed a number of differential proteins with similar expression patterns: CNOT2/9 and SHMT1 were found with high abundance in type B3 thymoma, while the abundance of HTRA1, TIMP1, and VCAN was higher in TSCC than in type B3 thymoma." (PMID 31967407, 2020).
viral infection (1 paper, 2022). "Furthermore, we found that the differentially interacting protein CCR4-NOT complex 2 (CNOT2), identified in PEDV S1 with plasma membrane proteins of Vero cells, is involved in viral infection." (PMID 36140672, 2022).
cancer (16 papers, 2019 to 2025). A tumor composed of atypical neoplastic, often pleomorphic cells that invade other tissues. "MID1-interacting protein 1 (MID1IP1) is highly expressed across various cancer types, with its involvement in cancer cell growth and apoptosis evidenced by its association with c-Myc-mediated ribosomal proteins L5, L11, and CNOT2." (PMID 40142004, 2025). "The precise molecular mechanisms governing CNOT2-mediated oncogenic signaling, its potential interaction with other cancer-associated pathways, and its context-dependent roles across different tumor types require further investigation." (PMID 40864769, 2025). "CNOT2 has been implicated in oncogenic processes, including mRNA degradation, apoptosis regulation, and ER stress response, highlighting its role in cancer progression." (PMID 40864769, 2025). "In summary, CNOT2 is implicated in cancer progression through its roles in mRNA degradation, apoptosis regulation, and ER stress response." (PMID 40864769, 2025). "The most frequently altered genes were CPD and CNOT2, whose overexpression was associated with survival, inhibition of apoptosis and angiogenesis in different cancer types." (PMID 31817495, 2019). "This review shows the essential roles of CNOT2 in maintaining cancer cellular homeostasis and explores its interactions within the CCR4-NOT complex that influence transcriptional and post-transcriptional regulation." (PMID 40864769, 2025). "Recent studies have shown that CNOT2 functions as an oncogene when proliferation and tumor angiogenesis was inhibited through Vascular Endothelial Growth Factor (VEGF) signaling are suppressed in CNOT2-suppressed human cancer cells." (PMID 40864769, 2025). "Recent studies have revealed the critical role of CNOT2 in cancer progression, highlighting its involvement in multiple oncogenic processes." (PMID 40864769, 2025). "MID1IP1, which induces apoptosis and is controlled by CNOT2, regulates c-Myc via ribosomal proteins L5 and L11, and is involved in cancer cell growth." (PMID 38139419, 2023). "A previous study reported that CNOT2 induces apoptosis in cancer cells by regulating c-Myc expression." (PMID 37550432, 2023). "Previous studies have revealed that CNOT2 is related to MID1IP1, which is associated with the regulation of c-Myc expression and apoptosis in cancer cells, and that CNOT2 knockdown induces apoptosis through MID1IP1." (PMID 37110707, 2023). "CNOT2 is also a novel candidate reference gene that was identified from pan-cancer transcriptome data." (PMID 37274277, 2023).
cancer (continued). "CNOT2 plays a crucial role in apoptosis, autophagy, proliferation, and angiogenesis in cancer cells." (PMID 38139419, 2023). "CNOT2 is associated with MID1IP1 in the regulation of c-Myc expression and the induction of apoptosis in cancer cells." (PMID 38139419, 2023). "CNOT2 is known to regulate cancer cell proliferation, metastasis, apoptosis, angiogenesis, and autophagy." (PMID 36569330, 2022). "Our studies reveal a new mechanism for its anti-cancer drug role in inhibiting c-Myc via CNOT2 or MID1IP1." (PMID 36233202, 2022). "Recent studies showed that inhibition of CNOT2 in human cancer cells inhibits cancer cell proliferation and angiogenesis through VEGF signaling in cancer cells, suggesting that CNOT2 acts as an oncogene." (PMID 34680125, 2021). "Consistently, CNOT2 was overexpressed in cancer cells as compared to normal cells (control) according to Western blotting." (PMID 34680125, 2021). "We found that the oncogenic role of CNOT2 is supported by the available bioinformatics databases because the high representation of CNOT2 was correlated with a low survival rate in cancer patients." (PMID 34680125, 2021). "We measured cell viability after inhibiting the expression of CNOT2 using CNOT2 siRNA to confirm that CNOT2 is related to cancer cell viability." (PMID 34680125, 2021). "CNOT2 has been identified as a key regulator in various cancer-related pathways." (PMID 40864769, 2025). "Inhibiting CNOT2 could effectively suppress tumor growth and metastatic progression, providing a multifaceted approach to cancer treatment." (PMID 40864769, 2025). "In addition, previous studies have shown that CNOT2 can regulate the expression of c-Myc and thus induce apoptosis in cancer cells." (PMID 40864769, 2025). "In this study investigated whether the MS extract exerted an anti-cancer effect by regulating c-Myc through CNOT2." (PMID 37550432, 2023). "Additionally, MID1IP1 contributes to cancer cell growth and death through co-localization with c-Myc-mediated ribosomal proteins L5, L11, and CNOT2." (PMID 38139419, 2023). "First of all, we checked the CNOT2 is related to cancer cell viability using CNOT2 siRNA." (PMID 34680125, 2021). "In summary, the current study demonstrates a new mechanism related to CNOT2 in cancer cells." (PMID 34680125, 2021).
cancer (continued). "Knockdown of CNOT2 inhibits cancer cell viability compared with the control group." (PMID 34680125, 2021). "First of all, we checked the expression of CNOT2 in cancer patient data from cBioportal." (PMID 34680125, 2021). "However, further study is required to evaluate the pivotal roles and protein–protein interaction (PPI) of MID1IP1 and CNOT2 in cancers via the Warburg effect in vitro and in vivo." (PMID 32316188, 2020). "Additionally, CNOT2 regulates c-Myc, a well-known oncogene, in cancer cells." (PMID 40864769, 2025). "Notably, recent studies indicate that CNOT2 depletion enhances chemosensitivity in certain cancer types, suggesting that targeting CNOT2 may improve treatment efficacy when combined with conventional anticancer agents." (PMID 40864769, 2025). "We also find that we are able to successfully transfer our cancer models to tumour-adjacent tissue when inspecting the top 6 genes explained by CNVs (i.e. LLPH, YEATS4, UQCRFS1, POP4, CNOT2, and CAND1)." (PMID 40041206, 2025). "CIAO1, CNOT2, and RBM45 were the candidate reference genes used in this study and were screened as stably expressed reference genes using pan-cancer transcriptome data." (PMID 37274277, 2023). "Our previous study showed that CNOT2 is related to MID1IP1 in regulating the expression of c-Myc and inducing apoptosis in cancer cells." (PMID 36233202, 2022). "CNOT2, a subunit of the CCR4-NOT complex, is known to be associated with apoptosis, angiogenesis, autophagy, and metastasis in several types of cancer cells." (PMID 34680125, 2021). "CCR4-NOT transcription complex subunit 2 (CNOT2), a subunit of the CCR4-NOT complex, has been described in cancer progression." (PMID 34680125, 2021). "Furthermore, CNOT2, a subunit of the CCR4-NOT complex, is known to be related to angiogenesis, metastasis, cell proliferation, and autophagy in many types of cancer cells." (PMID 36569330, 2022).
cancer (continued). "Additionally, utilizing compounds derived from natural products to target specific oncogenes such as c-Myc, CCR4-NOT transcription complex subunit 2 (CNOT2) and MID1-interacting protein 1 (MID1IP1) have been proposed as an innovative treatment for various cancers, particularly CRC." (PMID 38139419, 2023). "CNOT2 is a subunit of the CCR4-NOT complex that controls mRNA metabolism and the stability of eukaryotic cells and has been reported to play a role in autophagy, apoptosis, proliferation, and angiogenesis in various cancer cells, including those of the colon, lung, and breast." (PMID 36233202, 2022).
tumor (13 papers, 2016 to 2025). "Beyond its role in transcriptional and post-transcriptional regulation, CNOT2 has been implicated in drug resistance, immune evasion, and metabolic reprogramming, underscoring its potential as a key factor in tumor adaptation and therapy resistance." (PMID 40864769, 2025). "Future studies incorporating transcriptomics, proteomics, and metabolomics will be essential to validate CNOT2’s diagnostic and prognostic potential and to uncover its broader network-level interactions in various tumor contexts." (PMID 40864769, 2025). "Given its dual role in supporting oncogenesis or enabling tumor suppression depending on the cellular context, CNOT2 represents a compelling but nuanced target whose therapeutic exploitation will require precise, tumor-specific strategies." (PMID 40864769, 2025). "This tumor-type specificity highlights the importance of context-dependent investigations when evaluating CNOT2 as a therapeutic target." (PMID 40864769, 2025). "CNOT2 has been identified as a critical regulator of oncogenic pathways, contributing to tumor progression, immune evasion, and resistance to anticancer therapies." (PMID 40864769, 2025). "The results showed that CNOT2 was overexpressed more in tumor tissues than in normal tissues, indicating that CNOT2 regulates c-Myc expression in PC." (PMID 37550432, 2023). "Notably, studies indicate that CNOT2 modulates c-Myc stability, thereby impacting metabolic reprogramming and tumor cell proliferation." (PMID 40864769, 2025). "Additionally, given the dual role of CNOT2 in both oncogenic and tumor-suppressive mechanisms depending on the cellular context, future research should explore its function in a broader spectrum of malignancies." (PMID 40864769, 2025). "Furthermore, recent investigations suggest that CNOT2 contributes to immune evasion in tumors by regulating cytokine production and T-cell infiltration within the tumor microenvironment." (PMID 40864769, 2025). "Furthermore, in vivo modeling demonstrated that suppression or over-expression of CNOT2 within tumor cells resulted in enhanced or reduced pulmonary metastases, respectively, indicating that Cnot2 has metastasis suppressing activities." (PMID 26807845, 2016). "Interestingly, recent studies demonstrate that CNOT2 may exert opposite biological effects depending on tumor context." (PMID 40864769, 2025). "CCR4-NOT2 (CNOT2) plays a key role in apoptosis, autophagy, proliferation, and angiogenesis in various tumor cells." (PMID 37513375, 2023). "The data showed that the some of the candidate genes form chimeras with a variety of partners in different tumor types and the most frequently rearranged genes were CPD and CNOT2." (PMID 31817495, 2019). "In vivo validation studies demonstrated that varying CNOT2 levels significantly influenced tumor metastatic capacity and implicated the CCR4-NOT complex as a novel determinant of tumor cell metastatic potential." (PMID 26807845, 2016). "CNOT2, as a core component of the CCR4–NOT complex, has emerged as a key modulator of gene expression programs that influence proliferation, apoptosis, and metabolic adaptation in tumor cells." (PMID 40864769, 2025).
infection (2 papers, 2022 to 2024). The state of being infected such as from the introduction of a foreign agent such as serum, vaccine, antigenic substance or organism. "Similar to HNRNPM, RAI, LSM14A, LARP4, and CNOT2 showed complete loss of full-length protein during the course of infection." (PMID 38953667, 2024).
CNOT2 also shares sentences with these, for which no sentence is quoted: neurodevelopmental disorder (2 papers); Arrhythmia (1); breast tumors (1); cardiovascular diseases (1); heart disease (1); hypothyroidism (1); invasive breast carcinoma (1); learning disabilities (1); leukemia (1); Myocardial fibrosis (1); myocardial hypertrophy (1); neurodegenerative disease (1); T-cell acute lymphoblastic leukemia (1); thymic squamous cell carcinoma (1); ventricular dilatation (1); ventricular septal defect (1).